H19 (H19 imprinted maternally expressed transcript)
Diseases named in the same sentence as H19 in open-access papers (continued):
Sharing a sentence is not in itself a finding about the gene and the disease.
tumor (continued). "Moreover it has been shown that both H19 and LncROR can be transferred between cells via exosomes, leading to the increased activation of LIMK1 and TGFβ, respectively, in neighboring cells and thereby contributing to the spread of chemoresistance across the tumor microenvironment." (PMID 40781643, 2025). "The contradictory between H19 expression and functions in HCC may be explained that H19 functions as a hepatocarcinogenesis role at the initiatory stage of HCC but is then repressed by other factors, which depends on its context within the process of tumor progression." (PMID 36578923, 2022). "To confirm whether the inhibition of H19 and its target APOBEC3G would be effective in vivo, we used fertilized chicken eggs for tumor xenotransplantation, although we are aware that immunodeficient mice are the most common animal models for tumor transplantation." (PMID 33669381, 2021). "Interestingly, a study investigating the co-operation of H19 and miR-675 in HCC reported that knockdown of H19 and miR-675 promoted migration and invasion of HCC cells through the AKT/GSK-3β/Cdc25A signaling pathway, suggesting that H19 and/or miR-675 function as tumor suppressors." (PMID 32872482, 2020). "However, in adult cells, where it is not normally expressed, H19 could function as an oncogene by promoting tumor survival and metastasis." (PMID 31616462, 2019). "In addition, we found that there was a negative correlation between tumour volume and H19 level." (PMID 30397197, 2018). "As for H19, all tumor tissues except for one (ID 511) showed monoallelic expression, despite variation in iDMR methylation, strongly suggesting an absence of correlation between allelic expression of H19 and aberrant methylation of iDMRs within the IGF2/H19 domain." (PMID 30509319, 2018). "H19, an lncRNA aberrantly expressed in various malignancies, notably TNBC, orchestrates a complex array of mechanisms within the tumor microenvironment." (PMID 39286016, 2024). "As for the case of miRNA expression, the expression of H19, MALAT1 and BCL2 did not correlate in a statistically significant way with smoking status or tumor stage." (PMID 35723379, 2022). "Both lncRNA H19 and TNFAIP8 were significantly up-regulated in tumor tissues from TNBC compared with that in tumor tissues from non-TNBC and adjacent normal tissues." (PMID 32514245, 2020). "The one SDHAF2-related tumor without LOH for chromosome 11 by microsatellite marker analysis, demonstrated normal methylation of both H19-DMR and KvDMR, comparable to blood DNA." (PMID 28099933, 2017). "For the lncRNA H19 no significant expression changes overall were observed in either patient cohort, although individual NMIBC or MIBC tumour samples showed a clear upregulation." (PMID 28430799, 2017). "Among them, MALAT1, H19 and HOTAIR were significantly higher in plasma of tumor patients, while the other 3 lncRNAs showed no significant changes." (PMID 26096073, 2015). "The H19 and IGF2-P4 regulatory sequences are expected to be good candidates for specifically inducing the expression of DTA in target tumor cells but not in cells of normal tissue." (PMID 21162716, 2010). "Unlike MALAT1 and H19, MEG3 usually plays the role of a tumor suppressor." (PMID 33520725, 2020). "However, another study found decreased expression of H19 in the tumor tissue of HCC patients versus normal or non-tumorous adjacent tissue, and overexpression of H19 could suppress tumor growth and increase chemosensitivity." (PMID 39682684, 2024). "H19 and Meg3 are upregulated during the transition in vitro to in vivo in the presence of KSHV (KSHV (+) tumors versus KSHV (+) cells), but in this same transition in the absence of KSHV these lncRNAs are not upregulated (KSHV (−) tumors versus KSHV (−) tumor cells)." (PMID 34222014, 2021).
tumor (continued). "Furthermore, xenograft tumour studies in nude mice showed that the p-4E-BP1 levels were downregulated in vivo upon H19 overexpression and that p-4E-BP1 levels were increased in H19 knockdown tumours; mTORC1-mediated S6K1 phosphorylation, however, was not affected by H19 expression or knockdown." (PMID 30397197, 2018).
cancer (701 papers, 2005 to 2026). A tumor composed of atypical neoplastic, often pleomorphic cells that invade other tissues. "The upregulation of lncRNA with oncogenic potential such as HOTAIR, MALAT1, PCAT1, H19 have been reported in various cancer types and have been associated with various processes contributing to cancer development." (PMID 39912983, 2025). "H19 is implicated in cancer progression (proliferation, migration, invasion and metastasis), as well as endocrine therapy resistance, contributing to poor prognosis." (PMID 40868070, 2025). "H19, a cancer-embryo-associated lncRNA located on chromosome 11p15.5, acts as a pro-oncogene in many tumors." (PMID 40191723, 2025). "The imprinted and developmentally regulated H19 gene has been associated to a range of human cancers, although the underlying mechanisms are still poorly understood." (PMID 39912983, 2025). "Diverging into the realm of oncology, H19 has been implicated in various cancer types and has been studied for its dual roles as a tumor suppressor and a cancer promoter." (PMID 39156986, 2024). "The literature underscores the complexity of lncRNA H19′s involvement in cancer biology, particularly its association with autophagy and drug resistance mechanisms." (PMID 38794196, 2024). "H19 is intimately linked to cancer stem cell traits, potentially influencing self-renewal and differentiation through gene expression regulation." (PMID 39286016, 2024). "LncRNA H19 functions as an oncogene in numerous cancer types, including gastric, colorectal, pancreatic and BC, to the extent that plasma H19 has been proposed as a diagnostic and prognostic biomarker for BC." (PMID 39148900, 2024). "Although the association of H19 with various oncogenic signaling pathways in the regulation of PCD in cancer has been discussed in this review, certain deficiencies and problems remain, and further studies are needed to strengthen this link." (PMID 38355574, 2024). "In order to accurately assess the association between H19 polymorphisms and the risk of cancer, we conducted a comprehensive analysis of all relevant potential studies." (PMID 37480014, 2023). "Pre-miR-675 is a microRNA expressed from the exon 1 of H19 long noncoding RNA, and the atypical expression of pre-miR-675 has been linked with several diseases and disorders including cancer." (PMID 37624037, 2023). "It has been reported that the aberrant expression of H19 was implicated in various types of cancer, including breast, lung, esophageal, gastric, pancreatic, colorectal, liver, bladder and cervical cancer." (PMID 37480014, 2023). "H19 rs2107425 was related to lower cancer risk among Caucasians, while the rs2839698 was related to increased cancer risk among Asians." (PMID 37480014, 2023). "The abnormal expression of H19 is associated with various human cancers, including liver, gastric, pancreatic, and colorectal." (PMID 36960964, 2023). "A total of twenty-six studies with 12,413 cancer patients and 18,650 controls were included to examine the association between H19 SNP rs2839698 and cancer risk." (PMID 37480014, 2023). "In conclusion, this meta-analysis demonstrated significant associations between H19 rs2839698 and rs3024270 and overall cancer risk." (PMID 37480014, 2023). "Herein, a meta-analysis was carried out to better assess the relationship of H19 polymorphisms and cancer susceptibility." (PMID 37480014, 2023). "To explore the association between H19 rs3741219 polymorphism and cancer risk, we included 10 studies with 5305 patients and 6974 controls." (PMID 37480014, 2023). "LncRNA H19 is encoded by the H19 gene and plays a key role in cancer onset and progression modulating cell growth, invasion and migration." (PMID 37175546, 2023).
cancer (continued). "With a prior probability < 0.25, the H19 rs2839698 polymorphism was associated with the risk of cancer under allele, homozygote, dominant and recessive models." (PMID 37480014, 2023). "Emanating from diverse cancer cells, H19 is implicated in inflammation, stimulating pro-inflammatory cytokine release and extracellular matrix remodeling." (PMID 37760852, 2023). "Recent studies have focused on the association of single nucleotide polymorphisms (SNPs) in the H19 gene with the risk and prognosis of cancer." (PMID 36960964, 2023). "Up to now, the association between H19 and different types of cancers has been revealed for, i.e., breast, lung, oesophageal, colorectal, and bladder cancers." (PMID 37189829, 2023). "H19 is highly expressed in human ovarian tumor tissues and has been associated with cancer progression and poor patient prognosis." (PMID 38004379, 2023). "Third, each type of cancer with only one study was assigned to subgroup analysis by other cancers, and the number of included studies for certain H19 polymorphisms was relatively limited in the subgroup analysis." (PMID 37480014, 2023). "The association between the H19 rs2107425, rs2735971, rs3024270, rs3741219, and rs3741216 polymorphisms and cancer risk were separately examined in 13 studies, 8 studies, 15 studies, 13 studies, and 4 studies." (PMID 36588790, 2022). "The results showed that H19 rs2839698 polymorphism was associated with increased cancer risk in all participants under three genetic models." (PMID 36588790, 2022). "Based on these scientific developments, H19 has proven itself a diagnostic and therapeutic marker in various cancers, and its main role in carcinogenesis has been established." (PMID 36110523, 2022). "Previous reports proved that lncRNAs, such as H19, were associated with poor overall survival in a different type of cancers by promoting glycolysis." (PMID 34351577, 2022). "In conclusion, our results demonstrated that the H19 rs2839698 polymorphism increased cancer susceptibility, whereas the rs2107425 mutation decreased cancer susceptibility in the Caucasian population." (PMID 36588790, 2022). "Accumulating evidence has demonstrated that lncRNA H19 polymorphism was closely related to the initiation, development, and prognosis of cancer." (PMID 36588790, 2022). "The association between polymorphisms in lncRNA H19 and cancer susceptibility remains to be inconsistent." (PMID 36588790, 2022). "This study aimed to provide a more precise estimation of the relationship between lncRNA H19 polymorphisms and the risk of cancer based on all available published studies." (PMID 36588790, 2022). "In this sense, those clear-cut mechanisms underlying the H19 regulatory roles in the biological progression of cancer requires further investigation." (PMID 35955440, 2022). "Pooled ORs and their 95% CIs were used to estimate the strength between the SNPs in H19 (rs217727, rs2839698, rs2107425, rs3024270, rs2735971, rs3741216, and rs3741219) and cancer susceptibility." (PMID 36588790, 2022). "H19 is a 3.0 kb highly conserved lncRNA present on human chromosome 11; H19 polymorphisms are associated with increased susceptibility to a variety of cancers." (PMID 35719986, 2022). "Compared with normal fibroblasts (NFs), cancer-associated fibroblasts (CAFs) in CRC have higher levels of H19 expression." (PMID 36591473, 2022). "In summary, the rs217727, rs2839698, rs2107425 and rs2735971 polymorphisms in H19 have associations with cancer susceptibility." (PMID 36588790, 2022). "Compared to the loss of let-7a expression, the long non-coding RNA (lncRNA) H19 has been shown to be highly expressed in cancers, including GC." (PMID 34150620, 2021). "Expectedly, ectopic H19 expression was associated with shorter OS and lower complete remission, which was confirmed using the Gene Ontology Omnibus and The Cancer Genome Atlas datasets." (PMID 34421359, 2021).
cancer (continued). "For example, lncRNA H19, which is identified as the most variable gene in our analysis, is found to be associated with various cancer types." (PMID 34728653, 2021). "ALDH1A1 is a cancer stem cell marker in colon cancer cells, which suggests that H19 is also associated with the malignant potential of CRC stem cells." (PMID 34778084, 2021). "In colorectal cancer (CRC), H19 is upregulated and enriched in exosomes derived from cancer-associated fibroblasts (CAFs)." (PMID 33920605, 2021). "LncRNA H19 is an imprinted gene the aberrant expression of which is associated with cancer susceptibility." (PMID 34310645, 2021). "Sixteen studies about lncRNA H19 rs2839698 G>A ploymorphism and the susceptibility to cancer consisting 8872 cases and 11,723 controls met the inclusive criteria." (PMID 34310645, 2021). "Meanwhile, in the stratification analysis by genotypic method, apparent cancer risks were discovered by TaqMan method in H19 mutation rs2107425 and rs3024270." (PMID 34310645, 2021). "As previously reported in the literature, H19 polymorphisms were associated with the risk of several cancers." (PMID 34199840, 2021). "In this meta-analysis, we concentrated on the association between the overall cancer susceptibility and H19 mutation." (PMID 34310645, 2021). "A total of 10 studies embodying 11,468 cases and 16,555 controls were investigated to LncRNA H19 polymorphic variants rs2107425 C>T and the susceptibility to cancer." (PMID 34310645, 2021). "In recent years, the impact of H19 on cancer risk and prognosis has attracted researchers’ interest." (PMID 34199840, 2021). "An increasing number of studies have been focusing on the mutation of H19 when it comes to the genesis and development of various cancer." (PMID 34310645, 2021). "Further studies in all types of cancer across different populations are warranted to clarify the role of H19 polymorphisms in carcinogenesis." (PMID 33800276, 2021). "A previous genotype–phenotype correlation study showed that cancer-free controls carrying the variant genotypes (CT and TT) of H19 rs2839698 had a higher expression of H19 mRNA in serum than those with the wild-type CC genotype among 80 healthy controls." (PMID 33800276, 2021). "The dysregulation of H19 in gynecological cancers (ovarian, endometrial, and cervical cancer) is associated with several molecular pathways that are normally disrupted in cancer." (PMID 34204445, 2021). "Growing evidence implicates imprinted genes, including Igf2 and H19, which are typically known for their roles in early-life growth, to contribute to risk for cancers." (PMID 33445757, 2021). "The results about the associations between LncRNA H19 polymorphic variants (rs2839698, rs217727, rs2107425, rs2735971 and rs3024270) and the susceptibility to cancer were firm evidence of effect." (PMID 34310645, 2021). "Herein, this meta-analysis aimed at deriving a more accurate evaluation in all relevant published studies of the associations between the H19 SNPs and overall cancer susceptibility." (PMID 34310645, 2021). "Meta-analysis results for the included studies of the association between LncRNA H19 polymorphisms and risk of cancer." (PMID 34310645, 2021). "Our analyses showed that H19 is mainly associated with KEGG pathway of proteoglycans in cancer, tight junctions, and signaling pathways regulating the pluripotency of stem cells." (PMID 33584822, 2021). "It was demonstrated in another study that the rs217727 polymorphic site on H19 was associated with a certain cancer (OR = 1.31, 95%CI = 1.03 − 1.67)." (PMID 32337223, 2020). "Recently, several studies investigated the association between H19 gene rs2839698 polymorphism and the risk of cancers." (PMID 32207861, 2020). "To date, various studies have shown the association between H19 polymorphisms and several types of cancer." (PMID 32337223, 2020).
cancer (continued). "Several studies explored the association between the H19 gene rs2839698 polymorphism and the risk of cancers, but the findings concerning different types of cancers were conflicting." (PMID 32207861, 2020). "Recently, H19 has been demonstrated to be implicated in the regulation of CSCs in different types of cancers." (PMID 33291403, 2020). "To further explore the potential functionality of H19 rs2839698, we investigated the effect of this polymorphism on H19 expression in cancer tissues and paratumor normal renal tissues using real-time quantitative PCR." (PMID 32509581, 2020). "Many studies have shown an association between specific H19′s Single Nucleotide Polymorphisms (SNPs) and the overall cancer risk of squamous cell carcinoma, hepatocellular carcinoma, osteosarcoma, bladder cancer, gastric cancer, and breast cancer." (PMID 33335214, 2020). "Single-nucleotide polymorphisms (SNPs) in the H19 gene are associated with cancer susceptibilities and clinicopathologic features." (PMID 32878251, 2020). "LncRNA H19 is the first described human lncRNA and implicated in cancer initiation, progression and metastasis." (PMID 33267897, 2020). "In H19-deficient cells, expression of cancer stem-cell markers Prominin-1 (CD133), homeobox protein NANOG (NANOG), Octamer-binding transcription factor 4 (Oct4), and Sox2 are downregulated." (PMID 32650527, 2020). "Previous reports showed that the expression of H19 and miR675 was associated with cell apoptosis in cancer cells." (PMID 32323721, 2020). "In fact, several lncRNAs affected by cancer-relevant SNPs or amplifications and deletions, including H19, PVT1,or ANRIL have been implicated in cancer drug resistance, as extensively reviewed elsewhere." (PMID 33329688, 2020). "At present, many SNPs in H19 have been reported to be strongly associated with cancer susceptibilities, particularly polymorphisms at rs2839698, rs2107425, and rs2177727." (PMID 32878251, 2020). "The H19/IGF2:IG-DMR hypermethylation, for example, is coupled to the loss of imprinting of IGF2 and H19 in several congenital diseases and cancers, including WTs." (PMID 33217932, 2020). "H19 is enriched in carcinoma- associated fibroblasts (CAFs)-derived exosomes, which in turn promotes the stemness and chemoresistance of CRC cells by activating the β-catenin pathway via acting as a ceRNA sponge for miR-14145." (PMID 32242003, 2020). "Recently, a GWAS revealed that SNPs in H19 are associated with cancer susceptibility, and the correlation of H19 polymorphisms and cancers were confirmed in subsequent studies." (PMID 30890582, 2019). "Although only a small number of lncRNAs have been well-characterized, current studies have revealed that lncRNAs, such as H19 have been functionally associated with diseases occurrence, development, and progression, in particular, cancers." (PMID 31452627, 2019). "Downregulation of lncRNA H19 (H19) expression is associated with an unfavorable prognosis in some cancers." (PMID 31791180, 2019). "Recent functional studies provide insights into the roles of genetic variants in the H19 promoter region on the cancer risk, inter-individualized chemotherapy response and prognosis." (PMID 31452627, 2019). "Silencing H19 expression has been shown to cause a noticeable reduction in cancer cell proliferation and migration." (PMID 31164794, 2019). "Increased H19 allows cancer cells survive through treatment, and the implicated mechanism of H19 in regulation of BrCSCs’ division will reveal prospective approaches to constrain stem cells invasion." (PMID 30338598, 2019). "LncRNAs such as HOTAIR, MALAT1, GAS5, PC3, and H19 are aberrantly regulated in various malignant tumors and associated with carcinogenesis, metastasis, and prognosis." (PMID 31141943, 2019). "BWS is less frequently caused by activation of IGF2 and reduced H19 expression, although in these cases it is often accompanied by Wilms’s tumors and other cancers." (PMID 31143763, 2019).